FTO (FTO alpha-ketoglutarate dependent dioxygenase)
Diseases named in the same sentence as FTO in open-access papers (continued):
Sharing a sentence is not in itself a finding about the gene and the disease.
leukemia (continued). "Moreover, FTO overexpression upregulates the expression of survival and proliferation genes in an m6A-dependent manner, which contributes to the induction of tyrosine kinase inhibitor (TKI) resistance in leukemia cells." (PMID 34001273, 2021). "Importantly, combining FTO inhibitor treatment with existing therapeutic agents, such as standard chemotherapeutic agents or RTK inhibitors, enhances antitumor efficacy in leukemia patients, especially those with high FTO expression and relapsed/refractory AML." (PMID 34001273, 2021). "Moreover, FTO can also inhibit the expression of immune checkpoint genes, especially LILRB4, significantly weakening the self-renewal and reprogramming immune response of leukaemia stem cells/initiating cells, which has been proven to be an effective treatment strategy for AML." (PMID 39641872, 2024). "Knockout of FTO, but not ALKBH5, significantly suppresses leukemia initiation and progression." (PMID 40435251, 2025). "Interestingly, as R-2HG is structurally close to α-KG, it competitively inhibits the activity of α-KG-dependent dioxygease, FTO, thereby increasing the overall level of m6A without affecting FTO expression and decreasing the stability of MYC and CEBPA mRNA in R-2HG-sensitive leukemia cells." (PMID 34485297, 2021).
diabetes (151 papers, 2007 to 2026). "More recently, it has been shown that the polymorphisms of the FTO gene can contribute to several medical disorders, including cancer, diabetes mellitus, myocardial infarction, and renal failure." (PMID 41324103, 2025). "The m6A demethylase, fat mass and obesity-associated protein (FTO), has been implicated with multiple pathological processes, including diabetes mellitus, liver steatosis, leukemia, melanoma, and other various malignancies." (PMID 40642069, 2025). "Epidermis thinning in diabetes can be attributed to cell dysfunction and autophagy impairment caused by a decrease in FTO in keratinocytes." (PMID 40157922, 2025). "More recently, polymorphisms in the FTO gene have been found to be associated with a variety of diseases, including cancer, diabetes mellitus, heart attack, and kidney failure." (PMID 39758312, 2024). "The FTO gene’s impact varied with surgery type and duration, with some polymorphisms linked to weight loss differences, insulin levels, and diabetes risk." (PMID 39125390, 2024). "We also developed a novel macrophage membrane coated and PLGA-Dil based nanoplatform encapsulating FB23-2, an FTO inhibitor that suppresses diabetes associated endothelial phenotypes, thus providing a promising nanotherapeutic approach for DR." (PMID 38297099, 2024). "The combined impact of both a family history of diabetes and the rs8050136 variant of the FTO gene was found to increase the odds of developing GDM under all tested genetic models, after adjusting for gravidity." (PMID 38033012, 2023). "FTO gene alpha-ketoglutarate dependent dioxygenase linkage disequilibrium block Single-Nucleotide Polymorphism rs9939609 and rs9940128 threating inference was significant in the cancer and diabetes subjects correspondingly." (PMID 37471425, 2023). "Presumably, the mechanisms, by which, FTO controls vascular changes in retinopathy also underlies other micro- as well as macrovascular complications of diabetes." (PMID 37781923, 2023). "Decreased methylation rates of CpG sites are additionally reported with a higher risk of developing diabetes in patients with DMT2 when methylation levels of the FTO are lower." (PMID 37200795, 2023). "In this research, we identified an m6A demethylase, fat mass and obesity-associated protein (FTO), as an essential epitranscriptomic regulator in diabetes-induced vascular endothelial dysfunction." (PMID 37781923, 2023). "The FTO variant on chromosome 16 (rs11642015) is reported as pleiotropic SNP for inflammation and lipid traits, and associated with BMI adjusted diabetes." (PMID 36088317, 2022). "Although the association between FTO expression and diabetes has been affirmed, the potential of FTO in diabetic retinopathy remains to be elucidated." (PMID 35441575, 2022). "Thyroid function should also be regularly investigated based on the complex relationship between diabetes and thyroid dysfunction, as well as the role of FTO gene polymorphism in diabetes and thyroid dysfunction." (PMID 34258276, 2021). "The A-allele of FTO rs9939609 polymorphism in individuals with diabetes was associated with lower HDL-c (p = 0.008) and higher TG level (p = 0.007), and also the risk of cardiovascular disease was increased in the carriers of A-allele." (PMID 31996075, 2020). "The results of the present study demonstrated that FTO rs9939609 polymorphism has a relationship with the familial history of diabetes (P = 0.024), IR (P = 0.046), and T2D (P = 0.0001) in Northeast Iranian population." (PMID 31200723, 2019). "In the current study, both Omentin V109D and FTO rs9939609 polymorphisms had a relationship with IR and familial history of diabetes in the newly diagnosed T2D patients." (PMID 31200723, 2019). "Several meta-analyses have addressed the association between FTO SNP and risk of diabetes, hypertension, cardiovascular disease, polycystic ovary syndrome and mortality." (PMID 28881622, 2017).
diabetes (continued). "FTO has been confirmed as an important diabetes susceptibility locus associated with increased primary transcript levels of FTO mRNA." (PMID 26691922, 2015). "The main factors influencing body weight in children with diabetes include female gender, poor metabolic control, and carriage of the A allele of the FTO rs9939609 variant." (PMID 25214838, 2014). "Fat mass and obesity associated gene (FTO) is the first gene associated with body mass index (BMI) and risk for diabetes in diverse patient populations." (PMID 24877091, 2014). "Several groups have revealed that single nucleotide polymorphisms (SNPs) within the first intron of FTO are strongly associated with adiposity and diabetes by genome-wide association studies (GWAS)." (PMID 24877091, 2014). "After adjusting for age and gender, all of the FTO risk alleles were significantly associated with an increased susceptibility for diabetes in white individuals." (PMID 20502638, 2010). "Multivariable logistic regression models were used to examine the association of sequence variation in the FTO gene and diabetes case status." (PMID 20502638, 2010). "FTO-mediated RNA demethylation also drives diabetes-associated endothelial activation." (PMID 40771928, 2025). "Although the clinical association between FTO and diabetes has long been discussed, the roles and regulatory networks of FTO in DR remain unclear." (PMID 38297099, 2024). "However, the Finnish Diabetes Prevention Study (DPS) pointed out that the AA genotype FTO rs9939609 was associated with a 2.09-fold CVD in men with an abnormal glucose metabolism over a follow-up period of 10.2 years." (PMID 39257882, 2024). "However, further studies and clinical trials are warranted to fully validate the mechanisms underlying the FTO-mediated benefits in the setting of diabetes and subsequent vascular complications." (PMID 37781923, 2023). "This study’s results represent important translational implications that interfering FTO and its associated inflammation pathway might provide a promising therapeutic strategy for the vascular complications of diabetes." (PMID 37781923, 2023). "Furthermore, we described that endothelial loss of FTO alleviated diabetes-induced inflammation and angiogenesis in multiple ECs." (PMID 37781923, 2023). "It suggested that FTO may be a common genetic susceptibility gene for diabetes and thyroid dysfunction which caused the two diseases to overlap." (PMID 34258276, 2021). "Our data showed that each additional FTO A allele could alter the risk of diabetes with an OR of 2.6 and 95% CI of 1.87–3.04 when the case and control subjects are not matched in terms of BMI." (PMID 31200723, 2019). "In addition, both FTO rs9939609 and Omentin Val 109 Asp polymorphisms had a significant positive correlation with a familial history of diabetes (P = 0.024 and P = 0.046, respectively)." (PMID 31200723, 2019). "Additionally, both omentin Val109Asp and FTO rs9939609 polymorphisms were significantly positively correlated to familial history of diabetes (P = 0.046 and P = 0.024, respectively)." (PMID 31200723, 2019). "Nevertheless, the absence of an interaction effect in the trials indicates that, for the benefit of enhancing weight loss for diabetes prevention, there may be little clinical value in tailoring common lifestyle interventions to FTO genotype." (PMID 28124081, 2017). "In addition, the FTO variant is associated with diabetes-related metabolic traits (including higher fasting insulin, glucose and triglycerides, and lower HDL cholesterol), although the association disappeared after adjustment for BMI." (PMID 23977173, 2013). "Association of FTO risk alleles and diabetes stratified by race." (PMID 20502638, 2010). "The FTO rs9939609 variant, first detected in a genome-wide association study of diabetes, conferred an increased disease risk that was abolished after adjustment for BMI, suggesting that the association may be due to variation in adiposity." (PMID 20502638, 2010).
diabetes (continued). "Genetic variants in the FTO gene have consistently been reported to be associated with BMI and diabetes in Europeans, but the results have been variable for replication in other ethnicities including Hispanics, Asian and Oceanic populations, and African-Americans." (PMID 20502638, 2010). "Significant statistical interaction between race and the FTO variants suggests that the effect on diabetes susceptibility may be context dependent." (PMID 20502638, 2010). "Evidence of statistical interaction between race and the FTO polymorphism shown after combining African-American and white participants further suggests that the influence of the FTO gene on diabetes susceptibility may be context dependent." (PMID 20502638, 2010). "It is also worth further investigating whether FTO O-GlcNAcylation is associated with other aberrant FTO-mediated m6A-related diseases, such as diabetes mellitus, hepatic fibrosis, melanoma, and other various malignancies by using more mouse models and clinical samples." (PMID 40642069, 2025). "Third, based on any observed significant associations in the previous examination, we tested whether there is an association between FTO SNVs and cardiometabolic diseases (hypertension, history of stroke, heart disease, and diabetes) and whether this association varies by sex." (PMID 38064210, 2023). "Furthermore, a meta-analysis study conducted in South Asia showed that BMI and central obesity can partly account for the association of A allele of the FTO gene and diabetes, whereas this association was much reduced when adjusted for BMI in Europeans indicating ethnic-specific associations." (PMID 30170548, 2018). "Given the role of aldehyde chemistry in diabetes, the ability of FTO to form hm6A is of particular interest in this regard and is the subject of ongoing research." (PMID 40874592, 2025). "In patients with diabetes, a high-fat diet increases FTO expression, leading to reduced m6A methylation levels." (PMID 40356725, 2025). "The diabetes epidermis showed downregulation of FTO and upregulation of m6A compared to the normal epidermis layer in humans." (PMID 40157922, 2025). "Collectively, our data suggested that the FTO inhibitor, FB23-2, is a potential agent for diabetes correlated pathogenic endothelial phenotypes." (PMID 38297099, 2024). "We also found that FTO triggers diabetes-induced microvascular leakage by regulating EC-pericyte crosstalk." (PMID 38297099, 2024). "Some genes selected for this study, such as TCF7L2, FTO (rs9939609 variant), and CAPN10, have been shown to be associated with diabetes-related traits such as HbA1c levels, when diets are low in MUFAs and high in SFAs." (PMID 39275336, 2024). "Consistently, both NG2 and PDGFRβ staining demonstrated reduced pericyte coverage of retinal vessels upon the combination of FTO overexpression and diabetes." (PMID 38297099, 2024). "Uneven and tortuous retinal vasculatures were also observed upon the combination of FTO overexpression and diabetes in mice." (PMID 38297099, 2024). "Further morphological assessments identified that endothelial FTO overexpression and diabetes promote microglia activation, represented by an ameboid morphology, in a synergistic manner." (PMID 38297099, 2024). "To further annotate the role of FTO in regulating diabetes-induced microvascular dysfunction, we assessed retinal vasculatures in STZ mice receiving twice intra-vitreal injections of AAV-Fto." (PMID 38297099, 2024). "Endothelial FTO overexpression and diabetes also synergistically increased the soma area as well as decreased the territory projection area and number of interactions of microglia." (PMID 38297099, 2024). "FB23-2, which directly binds to FTO and selectively inhibits FTO’s m6A demethylase activity, suppressed diabetes induced endothelial phenotypes." (PMID 38297099, 2024).
diabetes (continued). "In conclusion, FTO plays a critical role in the pathogenesis of diabetes, influencing insulin secretion, insulin sensitivity, and the development of diabetic complications through diverse mechanisms." (PMID 39744011, 2024). "The association between genetic variants of FTO and diabetes underscores the complexity of the disease and highlights the potential of FTO as a biomarker and therapeutic target in managing diabetes and its complications." (PMID 39744011, 2024). "All three experiments consistently revealed that FTO overexpression aggravated diabetes-induced retinal vascular leakage." (PMID 38297099, 2024). "Collectively, above data suggested that FTO overexpression and diabetes regulated EC-pericyte crosstalk and aggravated microvascular pathology in a synergistic manner." (PMID 38297099, 2024). "FTO is regarded as an essential epitranscriptomic regulator in diabetes-induced vascular endothelial dysfunction." (PMID 39296713, 2024). "We found that diabetes and FTO overexpression decreased mRNA level of Tubb3 in mice neural retina in a synergistic manner." (PMID 38297099, 2024). "For example, instruments are from genes TCF7L2, IGF2BP2, NOTCH2, CDKAL1, PABPC4, FTO and JAZF1, known to be associated with diabetes and that have been further significantly associated with the metabolites." (PMID 39349772, 2024). "This study should be regarded as an initial exploration of the mechanisms of FTO-dependent RNA demethylation in diabetes-induced endothelial dysfunction." (PMID 37781923, 2023). "To determine the role of FTO in diabetes-induced retinal vascular endothelial dysfunction, we modulated its expression by intravitreal injection of adeno-associated virus (AAV) vectors containing overexpression plasmid or siRNAs." (PMID 37781923, 2023). "Hypomethylation of the FTO promoter along with the existing metabolic pathology (such as diabetes) contribute to altering foetal programming." (PMID 37200795, 2023). "Compared with that in control group, the diabetes-associated periodontitis group showed the largest increase in FTO expression, followed by that in the diabetes group." (PMID 37925419, 2023). "In this research, we observed elevated FTO stressed by high glucose not only in the ECs of retina, but also in other target organs of diabetes, such as heart and kidney." (PMID 37781923, 2023). "In the present study, TNIP1-NF-κB–mediated endothelial inflammation in diabetes was regulated by FTO." (PMID 37781923, 2023). "We explored the functional role of FTO in diabetes-induced retinal vascular endothelial dysfunction." (PMID 37781923, 2023). "In this study, we evaluated the relationship between FTO gene polymorphisms and TSH level in Uyghur patients with diabetes in Xinjiang." (PMID 34258276, 2021). "In our analysis, both MR + COLOC and MR + eCAVIAR have consistently shown evidence for causal effects on diabetes mediated by BMI for four genes (TFAP2B, TCF7L2, FTO and ZC3H4)." (PMID 32366963, 2020). "Both of the approaches (MR + COLOC and MR + eCAVIAR) have highlighted shared causal SNPs of BMI and diabetes for four genes (TFAP2B, TCF7L2, FTO and ZC3H4)." (PMID 32366963, 2020). "FTO was previously shown to be involved in several metabolic syndrome-related conditions such as diabetes, insulin signaling, lipogenesis, and mitochondrial dysfunction, whereby FTO overexpression was observed." (PMID 29922517, 2018). "Subsequently, an interaction effect was found between the diabetes-associated TCF7L genotypes and dietary fat/carbohydrate content, and also between FTO rs9939609 and macronutrient diet composition." (PMID 21695122, 2011). "Clinical characteristics and FTO SNP genotype frequencies in whites stratified by diabetes case status." (PMID 20502638, 2010). "Clinical characteristics and FTO SNP genotype frequencies in African-Americans stratified by diabetes case status." (PMID 20502638, 2010).